VDR (vitamin D receptor)
Diseases named in the same sentence as VDR in open-access papers (continued):
Sharing a sentence is not in itself a finding about the gene and the disease.
colon carcinoma (continued). "Specific mutations may cause deletions, frame-shift mutations, premature stop codons, or splice site abnormalities that down-regulate VDR expression and/or binding activity during colon cancer progression." (PMID 34359694, 2021). "Interestingly, in human colon carcinoma cell lines, the miR-372/373 cluster, which is upregulated by the Wnt/β-catenin pathway and enhances stemness, has been found to downregulate VDR RNA and a panel of differentiation genes." (PMID 32854355, 2020). "The crosstalk between 1,25(OH)2D3 and Wnt/β-catenin pathway has been reported in cancer cells, for example in vitro functional validation studies on melanoma and colon cancer cells showed that elevated 1,25(OH)2D3/VDR signaling inhibit Wnt/β-catenin signaling genes." (PMID 32554862, 2020). "Similar associations were observed for colon cancer, but not rectal cancer (P for interaction for the VDR complex and its transcriptional co-regulators and co-activators were 0.105 and 0.727, respectively)." (PMID 31434255, 2019). "Furthermore, miR-675-5p has been found overexpressed in metastatic colon cancer cells and it is able to induce resistance to 1,25(OH)2D3 by targeting VDR." (PMID 29149041, 2017). "We also showed that SNAIL1 RNA overexpression in colon tumors diminishes VDR RNA expression in the histologically normal tissue adjacent to the tumor, suggesting that SNAIL1-expressing colon cancer cells secrete signals that modulate VDR expression in neighboring cells." (PMID 26880977, 2016). "Indeed, the lowest VDR RNA levels were observed in those colon tumors that overexpress both EMT-TFs." (PMID 26880977, 2016). "VDR null mice do not develop GI or extra-colonic tumors but loss of VDR decreased intestinal tumor latency and increased progression to adenocarcinoma in both models." (PMID 27768599, 2016). "In addition to SNAIL1, we reported that its family member SNAIL2 represses VDR gene expression through the same E-boxes in the human VDR gene promoter and blocks the induction of an epithelial phenotype by 1,25(OH)2D3 in human colon cancer cells." (PMID 26880977, 2016). "In colon cancer, ligand-bound VDR also competes with transcription factors for β-catenin binding between the activator function-2 (AF-2) domain of VDR and the C terminus of β-catenin thus physically preventing transcriptional activation of TCF/LEF target genes." (PMID 26008979, 2015). "We observed that NOS2A, MMP1, and VDR were associated with survival after colon cancer diagnosis and no major angiogenesis genes on our platform were associated with rectal cancer." (PMID 25541970, 2014). "Indeed, the study of Evans and co-workers in the hepatic stellate cells and the work of Pike and co-workers in colon cancer cells both address this significant cross-talk of the VDR." (PMID 24860511, 2014). "Moreover, differentiation of colon cancer cells induced by various treatments occurs via upregulation of VDR." (PMID 24919507, 2014). "Accordingly, VDR expression is associated with high tumor differentiation, absence of node involvement, and good prognosis in colon cancer." (PMID 24202444, 2013). "In addition to colon cancer, VDR downregulation by Snail factors has been also observed in osteoblasts, osteosarcoma, breast cancer and renal cells." (PMID 24202444, 2013). "Mononuclear cells and various other cells in the body, including prostate, lung and colon cancer cells, contain 1α(OH)ase, the enzymatic machinery required to produce active vitamin D, which in turn works by binding to the vitamin D receptor (VDR), a specific nuclear receptor." (PMID 23875738, 2013). "In addition, VDR RNA expression in colon tumors inversely correlates with that of SNAIL1 and SNAIL2, suggesting that these transcription factors are responsible for the downregulation of VDR found in colon cancer." (PMID 24202444, 2013).
colon carcinoma (continued). "However, 1,25(OH)2D3 also plays an important role in cell cycle regulation in many cancers, including breast, ovarian and colon cancer, through its interaction with the VDR." (PMID 21592394, 2011). "In addition, we have studied the effect of VDR reconstitution in VDR-negative human colon cancer cells." (PMID 21858154, 2011). "However, the association between VDR expression and drug sensitivity in colon cancer cells was not clear." (PMID 31596728, 2019). "Interestingly, 14-3-3ζ/δ is also involved in regulation of Wnt/β-catenin signaling in intestinal stem cells, a pathway that is implicated in intestinal development and regeneration, and that has been associated with the differentiation-promoting effect of vitamin D/VDR in colon carcinoma cells." (PMID 24641763, 2014). "Furthermore, transient restoration of wild type VDR expression in VDR-negative human SW620 colon cancer cells decreases nuclear β-catenin level, whereas VDR-ΔAF2, VDR-L417S or VDR-E420Q mutants, unable to bind classical coactivators and activate gene transcription, did not." (PMID 21858154, 2011). "Other sup-group I receptor: The vitamin D receptor (VDR, NR1I1) and its interactions with Sp TFs play a role in the activation of p27Kip1 and CYP24A1 in colon cancer cells and CD14 in U937 cells." (PMID 39858066, 2025). "The synthesis of calcitriol analogues with blocked side chains has led to compounds with high vitamin D receptor (VDR) activation capacity, even higher than the natural ligand, in colon cancer cells." (PMID 41301826, 2025). "In our study, magnesium increased VDR expression in both normal colon fibroblasts and HCT-116 colon cancer cells." (PMID 41444742, 2025). "Previous studies have indicated that the oral consumption of Bb probiotics significantly decreased the levels of triglycerides, alkaline phosphatase, low-density lipoprotein, VDR, and LPR gene expression in mouse colon cancer." (PMID 37614602, 2023). "Moreover, in ApcPirc/+ rats, VDR loss did not enhance tumor multiplicity, growth, or progression in the colon, thus supporting previous findings that vitamin D itself does not play a role in colon cancer development or progression." (PMID 35889921, 2022). "Supporting this, VDR RNA expression correlates directly with differentiation and inversely with SNAI1 and SNAI2 RNA expression in human colon tumors." (PMID 32854355, 2020). "H19 can suppress vitamin D receptor (VDR) expression via miR-675-5p, and increased H19 leads to the resistance to 1,25(OH)2D3 treatment in the advanced colon cancer." (PMID 32117736, 2020). "Firstly, VDR enhanced the expression of transcription factors responsible for the increase in p27 gene expression, Sp1, and NFY, in SW620 colon cancer cell line and LNCaP prostate cancer cell line." (PMID 33291213, 2020). "We found that VDR was highly expressed in chemotherapy, BRAF inhibitors and PI3K-mTOR inhibitors resistant colon cancer cells." (PMID 31596728, 2019). "The major aim of the current study was to assess L. acidophilus and B. bifidum effects on the serum biochemical parameters, and the VDR and LPR genes in mice colon cancer." (PMID 31231490, 2019). "Oral consumption of L. acidophilus and B. bifidum probiotics significantly decreased the triglycerides, alkaline phosphatase, LDL, and also the VDR and LPR gene expression in mice colon cancer (P<0.005)." (PMID 31231490, 2019). "Spearman correlation demonstrated a positive correlation between VDR and CDX2 expression in three published GEO expression datasets derived from primary colon cancer patients." (PMID 31596728, 2019). "In the following, we assessed the effects of these probiotics on the gene expression of vitamin D receptor (VDR) and the leptin receptor (LPR) and the serum biochemical parameters on mice colon cancer." (PMID 31231490, 2019).
colon carcinoma (continued). "L. acidophilus and B. bifidum probiotics with the modification of the biochemical parameters and the expression of the VDR and LPR genes can play a key role in the protection of mouse colon cancer." (PMID 31231490, 2019). "For example, both VDR and CDX2 are highly expressed in chemotherapy, BRAF inhibitors and PI3K-mTOR inhibitors resistant colon cancer cells." (PMID 31596728, 2019). "In this respect, the present study was aimed to assess L. acidophilus and B. bifidum impacts on the VDR and LPR gene and the serum biochemical parameters on mouse colon cancer." (PMID 31231490, 2019). "Overall, our results showed a molecular sub-cluster of colon cancer cells with low CDX2 and VDR expression was sensitive to chemotherapy, BRAF inhibitors and PI3K-mTOR inhibitors treatment." (PMID 31596728, 2019). "We find that a molecular sub-cluster of colon cancer cells with low CDX2 and VDR expression is specifically sensitive to chemotherapy, BRAF inhibitors and PI3K-mTOR inhibitors treatment." (PMID 31596728, 2019). "We have also described that human VDR gene is a direct target of SNAIL1 and SNAIL2/SLUG transcription repressors, and that VDR expression in colon cancer patients is reduced at advanced stages of the disease associated to the upregulation of these factors." (PMID 21858154, 2011). "Furthermore, these probiotics decreased vitamin D receptor (VDR) and leptin receptor (LPR) gene expression levels in colon tumors." (PMID 41237260, 2025). "Regulation of VDR, LPR, and lipid parameters play a key role in the development of colon cancer." (PMID 41237260, 2025). "Similarly, the rs11064124 G > A influences the binding of the vitamin D receptor (VDR), resulting in reduced expression of the tumor suppressor genes CD9 and PLEKHG6, ultimately promoting the development of colon cancer." (PMID 38902506, 2024). "However, the role of VDR and PXR/SXR in CRC is still controversial, and more studies are necessary to clarify their activities in colon cancer cells." (PMID 35889921, 2022). "This study demonstrates that the vitamin D receptor does not impact tumor development, and strongly supports previous findings that vitamin D itself does not play a role in colon cancer development or progression." (PMID 35662320, 2022). "We summarize studies related to VDR/TJ distribution, cellular functions, and mechanisms; we discuss the role of VDR and barriers in various diseases, e.g., IBD, colon cancer, chronic obstructive pulmonary disease (COPD), infection, and other diseases, mainly focusing on the intestinal diseases." (PMID 35406694, 2022). "The pattern of hypermethylation of the VDR promoter region is inconsistent in cancer cell lines; for example, colonic cancer cells do not reveal a hypermethylated status in the VDR promoter region." (PMID 33291213, 2020). "It has been reported that curcumin has a structure suitable to bind nuclear vitamin D receptor and plays a role in colon cancer chemoprevention thanks to this property but no specific experiments have been performed by the authors to confirm this finding." (PMID 30759785, 2019). "Moreover, there is a positive correlation between VDR and CDX2 expression in primary colon cancer patients." (PMID 31596728, 2019). "All those VDR expression features were quite similar with CDX2, so we speculated that VDR was also an important prognostic biomarker for colon cancer patients." (PMID 31596728, 2019). "Overall, our results suggest a molecular sub-cluster of colon cancer cells with low CDX2 and VDR expression is sensitive to chemotherapy, BRAF inhibitors and PI3K-mTOR inhibitors treatment and provide an example of translation of cancer classification to subgroup guided therapies." (PMID 31596728, 2019). "Besides colon cancer, it was demonstrated that JNK1 cooperates also with p38 (another mitogen-activated protein kinase), activating VDR and increasing 1,25(OH)2D-dependent growth inhibition in breast cancer cells (MCF-7)." (PMID 28427151, 2017).
colon carcinoma (continued). "Here we unveil that 1,25(OH)2D3-bound VDR activates Silent Information Regulator of Transcription, sirtuin 1 (SIRT1), leading to β-catenin deacetylation and nuclear exclusion, downregulation of its pro-tumourigenic target genes and inhibition of human colon carcinoma cell proliferation." (PMID 39494323, 2024). "In addition, cross-inhibition of VDR and EGFR has been described in colon carcinoma cells." (PMID 32854355, 2020). "In addition, while mouse embryonic fibroblasts lacking VDR showed higher NF-kB activity, in colon cancer cells exposed to lithocholic acid, a VDR ligand, a downregulated NF-kB activity has been reported." (PMID 32560347, 2020). "And the sub-cluster of colon cancer patients with lack of VDR expression could benefit from adjuvant chemotherapy, BRAF inhibitors and PI3K-mTOR inhibitors treatment." (PMID 31596728, 2019). "Thus, an oral consumption of L. acidophilus and B. bifidum probiotics could be effective on the serum biochemical parameters, and the VDR and LPR genes in mice colon cancer." (PMID 31231490, 2019). "And a sub-cluster of colon cancer patients with lack of VDR expression could benefit from adjuvant chemotherapy, BRAF inhibitors and PI3K-mTOR inhibitors treatment." (PMID 31596728, 2019). "The repression of VDR gene by SNAIL factors is not exclusive to colon cancer." (PMID 26880977, 2016). "From these data we speculate that up-regulation of CYP24A1 in the tumor is uncoupled from VDR, and therefore is independent of the local levels of 1,25(OH)2D3, as it has been suggested for benign and malignant tumors of the colon." (PMID 25090635, 2014). "According to data from cultured cells and animal models, we found a significant direct correlation between VDR and CDH1/E-cadherin RNA levels in human colon tumors, suggesting that VDR/1,25(OH)2D3 may contribute to the restoration of normal E-cadherin levels in human colon cancer." (PMID 24202444, 2013). "In HFD-fed Cdx2Apcf/w mice, BSHhigh BF activated the TGR5 pathway in colon tumor tissues but did not increase FXR and VDR signaling." (PMID 36765047, 2023).
colorectal cancer (106 papers, 2005 to 2026). A primary or metastatic malignant neoplasm that affects the colon or rectum. "BACKGROUND: Circulating 25-hydroxyvitamin D [25(OH)D] levels and genetic polymorphisms in the vitamin D receptor (VDR) have been explored as potential prognostic factors in colorectal cancer (CRC)." (PMID 41987077, 2026). "In fact, clinical studies in colorectal cancer have shown that SNAIL expression is associated with a decrease in VDR and CDH1, a correlation that is lost in the presence of high levels of ZEB1." (PMID 41301826, 2025). "Colorectal cancer susceptibility increases when the VDR is dysregulated, a condition that can be induced by PFAS through their binding to the VDR, as well as to other nuclear receptors." (PMID 39125814, 2024). "Sex-stratified analysis showed that cumulative methylation status at significant CpG sites of VDR was significantly associated with lower risk of colorectal cancer in both males and females." (PMID 37644572, 2023). "The methylation status at significant CpG sites of VDR was negatively associated with the risk of colorectal cancer, with aOR of 0.28 (95% CI, 0.16–0.51; P < 0.001)." (PMID 37644572, 2023). "A significant association was found between VDR methylation and VDR expression in colorectal cancer progression." (PMID 38203278, 2023). "Vitamin D binds to and activates nuclear vitamin D receptors (VDR), causing transcriptional activation and repression of the target genes, and an association of the VDR BsmI polymorphism with colorectal cancer has been observed." (PMID 34360782, 2021). "Previous studies have also been conducted to find the link of VDR polymorphisms in relation to colorectal cancer." (PMID 34200111, 2021). "High VDR expression in tumor stromal fibroblasts was associated with better overall survival and progression-free survival in patients with colorectal cancer, independently of its expression in carcinoma cells." (PMID 34572935, 2021). "The results showed that the NES mutation of VDR inhibited the self-renewal of colorectal cancer stem cells under acidic conditions." (PMID 32900990, 2020). "The aim of the current study was to assess the relationship between serum vitamin D metabolite and calcium levels with VDR polymorphisms in normal and colorectal cancer (CRC) patients." (PMID 31534963, 2019). "Genes such as CD82 and S100A4, which are responsive to calcitriol in CAFs, are also associated with clinical outcomes and stromal VDR expression in patients with colorectal cancer, supporting a clinical value of VDR agonists in cancer treatment." (PMID 30925918, 2019). "The association of VDR FokI polymorphism with colorectal cancer risk was analyzed using a logistic regression model." (PMID 30150667, 2018). "To investigate the association between VDR FokI and colorectal cancer, we conducted both a case-control study and a meta-analysis of 16 previous studies." (PMID 30150667, 2018). "In this case-control study, a total of 200 subjects were examined for four SNPs in the VDR gene to determine the risk of predisposition to colorectal cancer." (PMID 27309378, 2016). "Previous studies demonstrated that VDR gene polymorphisms, which include FokI, BsmI, ApaI, TaqI, and Cdx2, are associated with ovarian, skin, breast, and colorectal cancers." (PMID 27553621, 2016). "Association of VDR and GC gene polymorphisms with colorectal cancer risk according to plasma vitamin D concentration." (PMID 27736940, 2016). "In conclusion, this is the first study to assess the role of VDR polymorphism in the risk of developing colorectal cancer in Saudi Arabian population." (PMID 27309378, 2016). "We next examined the role of the VDR in colorectal cancer caused by the colon chemical carcinogen, azoxymethane (AOM)." (PMID 27768599, 2016). "Here, using a tag SNP approach, we comprehensively evaluated the role of common genetic variants in VDR and their interaction with plasma vitamin D levels in relation to colorectal cancer risk in Japanese populations." (PMID 27736940, 2016).